RN7SL712P (RNA, 7SL, cytoplasmic 712, pseudogene)
Gene: Miscellaneous RNA gene on chromosome X (115,992,466 to 115,992,773, reverse strand). Ensembl gene ENSG00000266828.
Homologues: Orthologues: chimpanzee Metazoa_SRP (98% identical), macaque Metazoa_SRP (86% identical), rabbit Metazoa_SRP (65% identical). Paralogues in human: RN7SL1 (85% identical), RN7SL2 (84% identical), RN7SL3 (82% identical), RN7SL769P (80% identical), RN7SL127P (80% identical), RN7SL113P (80% identical), RN7SL336P (80% identical), RN7SL45P (80% identical), RN7SL559P (80% identical), RN7SL804P (80% identical), RN7SL186P (79% identical), RN7SL246P (79% identical), and 704 more.